CDKN2A (cyclin dependent kinase inhibitor 2A)
Diseases named in the same sentence as CDKN2A in open-access papers (continued):
Sharing a sentence is not in itself a finding about the gene and the disease.
cancer (continued). "Located on chromosome 9, CDKN2A plays a crucial role in inhibiting cell proliferation and invasion across cancers." (PMID 38666907, 2024). "We combined the five cancer types with the highest CDKN2A ALT frequency in the MSK-MetTropism cohort and the TCGA cohort." (PMID 38822443, 2024). "Among the 37 types of cancers in the merged cohorts, 23 cancer types with CDKN2A ALT exhibited shorter OS compared to CDKN2A-WT patients." (PMID 38822443, 2024). "Building upon the foundational work in the field, our findings echo and extend the narrative around CDKN2A's prognostic significance in cancer." (PMID 38751024, 2024). "Results revealed that of the 20 tumors examined in this research, 15 tumors showed high levels of CDKN2A expression in cancer tissues compared to control tissues (p < 0.05)." (PMID 38206516, 2024). "Even CDKN2A, with a low prevalence and relatively modest cancer effect, is potentially highly relevant for the epistatic effects that its mutated form exerts on other mutations." (PMID 38928295, 2024). "Based on a meta-analysis of 734 PTC patients, it was found that cancer tissues had significantly more CDKN2A promoter methylation than benign and normal tissues." (PMID 38329430, 2024). "Loss of 9p21 locus that harbours CDKN2A and ARF tumour suppressor genes occurs in the very early stages of cancer initiation from the normal mucosa to hyperplasia." (PMID 38643337, 2024). "LEF1, WT1 and BCL11B copy number abnormalities were reported from the TARGET study of 2471 pediatric cancer patients whereas in our group we found CDKN2A, CDKN2B and MTAP harboring most copy number variations." (PMID 38459434, 2024). "For example, the hypermethylation of the cyclin dependent kinase inhibitor 2A (CDKN2A) gene promoter, which encodes the tumor suppressor p16, is a common feature in many cancers." (PMID 39056791, 2024). "The outcomes of this study’s investigation indicated that CDKN2A expression difference was observed between cancer tissues and control tissues of 15 kinds of tumors, and all showed high expression." (PMID 38206516, 2024). "In this study, the gene expression of the vast majority of CuRGs was downregulated in most cancers, except for CDKN2A, which was upregulated." (PMID 38573998, 2024). "In the MSK-MetTropism cohort, CDKN2A ALT had a worse prognosis in most primary cancer types than metastatic." (PMID 38822443, 2024). "We used 1661 patients from the MSK-IMPACT cohort treated with ICIs to assess changing effect of CDKN2A ALT on clinical outcomes of some cancer types after immunotherapy." (PMID 38822443, 2024). "CDKN2A is affected in about 10% of all cancers with the highest prevalence of alterations observed in lung adenocarcinoma, pancreatic adenocarcinoma, conventional glioblastoma multiforme, cutaneous melanoma, and bladder urothelial carcinoma." (PMID 38561743, 2024). "Then, we looked into the genetic alteration of CDKN2A by using the cBio Cancer Genomics Portal (cBioPortal), including 10 pan-cancer studies." (PMID 38894777, 2024). "As an oncogene, cyclin-dependent kinase inhibitor 2A (CDKN2A) can encode p16 and p14, often expressed as homozygous deletions in a variety of cancers, such as oral squamous cell carcinoma and melanoma 48,49." (PMID 39309446, 2024). "Therapeutically, targeting the disrupted cell-cycle regulation by CDKN2A variants is explored through CDK4/6 inhibitors, showing promise in various cancers; although, the impact of CDKN2A status on treatment response requires further exploration." (PMID 38666907, 2024).
cancer (continued). "Among them, the expressions of Cdkn1a, Hmga2, Thbs1 and Cdkn2a in MicroRNAs that promote cell differentiation in cancer pathways increased, indicating that the differentiation of SSCs is dominant." (PMID 38397131, 2024). "CDKN2A showed a highly significant differential expression in various types of cancer, including 10,000 samples." (PMID 38894777, 2024). "Meanwhile, NCCN_cancer targets were mainly composed of ERBB2 amplification (40%), BRCA2 pathogenic mutations (40%), and CDKN2A oncogenic mutations (20%)." (PMID 38661052, 2024). "Third, the lack of CDK4/6 inhibitors treatment limited the analysis of interaction effects between ICIs and CDK4/6 inhibitors on clinical outcomes of pan-cancer patients with CDKN2A ALT." (PMID 38822443, 2024). "CDKN2A is considered a suppressive oncogenic gene in most types of cancer, with various variations related to the patient’s overall survival and its expression." (PMID 38894777, 2024). "Three cancer types were eventually identified and survival analyses were performed, and it was found that CDKN2A-ALT had a worse OSin PAAD and MESO except HNSC." (PMID 38822443, 2024). "BRAF and MEK inhibitors are commonly used in combination treatments for other cancers with high rates of RAS and CDKN2A mutations." (PMID 38612819, 2024). "CDKN2A has multifaceted involvement in cancer, encompassing its regulatory function and effects on different cancer types." (PMID 38774759, 2024). "Various cancer predisposition genes, including BRCA1, BRCA2, and p16/CDKN2A, have already been identified in high-risk pedigrees." (PMID 38894738, 2024). "One of the most common sporadic homozygous deletions in cancers is 9p21 loss, which includes the genes methylthioadenosine phosphorylase (MTAP), CDKN2A, and CDKN2B, and has been correlated with worsened outcomes and immunotherapy resistance." (PMID 38330461, 2024). "MTAP encodes the metabolic enzyme methyl-thio-adenosine phosphorylase; it is homozygously deleted in 15% of cancers, and frequently co-deleted with the tumour suppressor CDKN2A at the 9p.21 genomic locus." (PMID 38755480, 2024). "Overall, CDKN2A ALT remain an important area of research in cancer immunotherapy, and further studies are needed to clarify the role of CDKN2A mutations/deletions as potential biomarkers for ICI treatment." (PMID 38822443, 2024). "In Non-small Cell Lung Cancer (NSCLC), NXPH4 is regulated by its upstream transcription factor E2H2, which promotes cancer cell proliferation and invasion by altering the structure of CDKN2A." (PMID 38613793, 2024). "As an example, telomerase and p16INK4a (p16, cyclin-dependent kinase inhibitor 2A) are representative epigenetic targets that feature in both aging and cancer scenarios." (PMID 38474354, 2024). "Dysregulation of CDKN2A, often observed through genetic and epigenetic alterations, is a common feature in various cancers, leading to uncontrolled cell proliferation and survival." (PMID 38666907, 2024). "By comparison, effective and relatively non-invasive cancer surveillance programs are available to CDKN2A PV carriers." (PMID 38822936, 2024). "In the context of cancer, initial studies revealed that PcG proteins act as oncogenes through the transcriptional repression of the INK4A/ARF (CDKN2A) tumour suppressor locus." (PMID 39174513, 2024).
cancer (continued). "Hypermethylation of the CDKN2A promoter is a confirmed marker of CDKN2A inactivation, playing a significant role in malignant tumor development." (PMID 39001498, 2024). "Among other causes, p16 overexpression in cancer cells has been related to RB1 loss of function, which prevents the CDKN2A locus silencing by Polycomb Repressor Complexes and trimethylation of lysine 27 on histone H3 by EZH2." (PMID 36453028, 2024). "Our study demonstrates the pan-cancer relevance of CDKN2A and revealed a novelty in showing CDKN2A underscores its potential as a diagnostic prognostic biomarker in COAD since CDKN2A is mostly studied at a genetic level across COAD." (PMID 38894777, 2024). "Other genes reported as cancer related in COSMIC (v98) showing high proportions of shared non-synonymous mutations were MUC16 (10 patients), FAT4 (6 patients) and CDKN2A (7 patients)." (PMID 39020404, 2024). "In this context, CDKN2A has been investigated in numerous cancer types to reveal its functions in carcinogenesis." (PMID 38164368, 2024). "CDKN2A is located on the human chromosome 9p and is deleted or epigenetically silenced in many cancer types, including HCC (2017)." (PMID 37261974, 2023). "Studies have showed that CDKN2A is significantly expressed in multiple cancer tissues, thus affecting the prognosis of a variety of cancers." (PMID 36891559, 2023). "CDKN2A encodes for two separate proteins p14 and p16 (INK4a) and is involved in cell cycle regulation, and a loss of function of CDKN2A is associated with cancer." (PMID 37434653, 2023). "Our results suggest that CDKN2A has the potential to infer the efficacy of ICIs in corresponding cancers." (PMID 36961395, 2023). "CDKN2A is the second most commonly deactivated tumor suppressor gene and it plays a prominent role in many common malignant tumors." (PMID 36961395, 2023). "Copy number deletions of cancer suppressor genes (including CDKN2A/B, FOCAD, NF2, etc.)are always accompanied by adjacent functional genes (including MTAP, MLLT3, etc.)deletion that synergistically contributes to oncogenesis." (PMID 37033966, 2023). "Even though researchers are suggesting that CDKN2A plays a vital role in drug resistance in a variety of cancer types, its exact role and mechanism remain imprecise." (PMID 37415453, 2023). "Zhao R., Choi B.Y., Lee M.H., Bode A.M., Dong Z. Implications ofgenetic and epigenetic alterations of CDKN2A (p16INK4a) in cancer.EBioMedicine." (PMID 36923482, 2023).
cancer (continued). "CDKN2A led to the highest mutation frequency in most cancer types, and UCEC had the highest mutation frequency among all cancer types." (PMID 36766692, 2023). "In our study, CDKN2A has been found to be a stable prognostic biomarker for pan-cancer and can effectively predict the response to ICI treatment." (PMID 36961395, 2023). "The volcano plot of DEGs between 11 wart and 7 cancer samples of patients with EV shows differential expression of cancer-associated genes, such as FOS, JUND, PCNA, CHEK1, and CDKN2A." (PMID 36602881, 2023). "We demonstrated the potential components of targeted CDKN2A in pan-cancer in the form of heat maps using data downloaded from the CMap dataset." (PMID 36961395, 2023). "Prior reports have demonstrated that CDKN2A is frequently altered across brain metastases from several cancer types." (PMID 36915611, 2023). "In contrast, eight regulators (PDHA1, ATP7A, LIPT1, LIPT2, GLS, ATP7B, GCSH, and CDKN2A) were upregulated in cancer tissues." (PMID 36672336, 2023). "In most TCGA cancers, CDKN2A is positively correlated with the degree of infiltration of CD4+ T cells, NKT cells, Tregs, neutrophils, and macrophages." (PMID 36961395, 2023). "It has been suggested that frequent chromosomal losses of JAK2 is a result of co-deletion with the tumour suppressor gene CDKN2A on chromosome arm 9p across cancer types." (PMID 37837931, 2023). "It is important to note that CDKN2A deletion can be acquired already at the low-grade step before becoming an aggressive cancer, and then, being used as a supplementary and independent prognostic biomarker in those clinical situations." (PMID 36831610, 2023). "We analyzed CDKN2A expression in 34 human cancers using the UCSC database in order to explore possible effects of CDKN2A on cancer incidence and development." (PMID 37950153, 2023). "A comparative analysis of the CDKN2A gene expression was performed on cancer and normal samples using the GEPIA and UALCAN databases." (PMID 37950153, 2023). "We constructed a heatmap to show the prognosis analysis results (including univariate Cox and Kaplan-Meier methods) of CDKN2A in pan-cancer, and we found that CDKN2A has strong prognostic correlations with most cancers except TGCT." (PMID 36961395, 2023). "Cancers carrying BRAF mutations have increased the expression of cell cycle inhibitors, including CDKN2A, CDKN1A, and CDKN1B." (PMID 38020918, 2023). "The loss of FH causes hypermethylation in the promoter of the tumor suppressor cyclin-dependent kinase inhibitor 2A (CDKN2A), the hypermethylation of CDKN2A is a predictive factor for unfavorable prognosis of various cancers." (PMID 36778129, 2023). "Because CDKN2A alterations have been reported in different types of human tumors, the current study was performed in a pan-cancer model." (PMID 37626750, 2023). "In the differential expression analysis of oral squamous cell carcinoma and adjacent tissues, LIAS and PDHB were inhibited in cancer tissues, while GLS and CDKN2A were promoted in cancer tissues." (PMID 36600313, 2023). "We found CDKN2A is overexpressed in most cancers and exhibits prognosis predictive ability in various cancers." (PMID 36961395, 2023). "But the role of CDKN2A in cancer immune infiltrations and immunotherapy response prediction is not clear." (PMID 36961395, 2023).
cancer (continued). "Then we conducted genomic alteration analysis of CDKN2A and found the alterations frequency of CDKN2A across pan-cancer are generally high, alteration frequencies of 14 cancers are more than 10%." (PMID 36961395, 2023). "We classified the cancer cells into the five cancer subtypes as CDKN2A, SOX2, CXCL1, LAMC2, and proliferating cancer based on the top markers that are highly expressed in each cluster." (PMID 36973297, 2023). "The MTAP gene, which is located at the chromosomal locus 9p21, is deleted in many human cancers because of its proximity to the tumor suppressor gene cyclin-dependent kinase inhibitor 2A." (PMID 36831453, 2023). "In order to analyze the fundamental information of CDKN2A in cancers, we used the transcriptomic data obtained from TCGA and GTEx databases to assess the mRNA expression levels of CDKN2A in cancers compared with human normal tissues." (PMID 36961395, 2023). "Collectively, the current study demonstrates the potential employment of CDKN2A genetic alteration as a prognostic and immunological biomarker under several types of human cancers." (PMID 37626750, 2023). "Further analysis on cancer cell-specific genes revealed that KPmut-Late tumors exhibit elevated expression levels of several genes, including Prkg2, Hmga2, Wincr1, Cdkn2a, Tnnt2, Aqp5, and Sprr1." (PMID 37998349, 2023). "We found that in the majority of carcinomas, the CRGs were poorly expressed in tumors, except for CDKN2A." (PMID 37006250, 2023). "CDKN2A (p16) expression is a predictive marker for HPV infection, and as such, practically all HPV-associated cancers overexpress p16." (PMID 35884575, 2022). "CDKN2A was previously thought to induce cell cycle arrest in both G1 and G2 phases, and its inactivation is an important event in many cancer types." (PMID 36384423, 2022). "MTAP loss in GBM has its impact on multiple aspects—co-deletion of CDKN2A, prognosis, metabolism pathway, immunosuppressive profile, and cancer cell stemness among others." (PMID 36572880, 2022). "In addition to missense mutations and other mutation types, the CDKN2A gene is frequently affected by nonsense mutations, in line with our analysis, which demonstrates that R80*, R58*, W110*, E120*, Y44* and E88* together constitute almost a third of cancer cases that harbor a defective CDKN2A gene." (PMID 35158934, 2022). "As typical tumor suppressor genes (TSGs), the cyclin‐dependent kinase inhibitors CDKN2A and CDKN2B located on chromosome 9, band p21.3, are frequently mutated, deleted, or dysregulated in a variety of cancers." (PMID 35253368, 2022). "In primary cancer we found that CDKN2A was predominantly clonal in three cancer types (BLCA, HNSC and LUNG)." (PMID 36497297, 2022). "Since mRNA expression of Cdkn1a and Cdkn2a, which are representative senescence marker genes, is regulated by UHRF1 in lymphocytes and cancer cells, the cellular phenotypes caused by UHRF1 depletion can resemble those of cellular senescence." (PMID 35472067, 2022). "In the present study, we initially found the 8~17 kd estimated CDKN2A CDR in both monoclonal cancer cell lines and cell-heterogeneous cancer tissues with CDKN2A copy number deletion according to the SNP-array datasets from COSMIC and TCGA projects." (PMID 36531022, 2022).